MEX3C (mex-3 RNA binding family member C)
Description:
E3 ubiquitin ligase responsible for the post-transcriptional regulation of common HLA-A allotypes. Binds to the 3' UTR of HLA-A2 mRNA, and regulates its levels by promoting mRNA decay. RNA binding is sufficient to prevent translation, but ubiquitin ligase activity is required for mRNA degradation.
Synonyms: RKHD2; RNF194; BM-013; FLJ38871; MEX-3C
Tractability: PROTAC: ubiquitination databases record sites on it.
Gene: Protein-coding gene on chromosome 18 (51,174,550 to 51,218,333, reverse strand). Ensembl gene ENSG00000176624.
Subcellular location: Cytoplasm; Nucleus
Subcellular location (Human Protein Atlas): Vesicles
Pathways (Reactome):
Immune System: Antigen processing: Ubiquitination & Proteasome degradation
Gene Ontology:
Molecular function: protein binding; RNA binding; ubiquitin protein ligase activity; nucleic acid binding
Cellular component: cytoplasm; nucleus
Genetic constraint (gnomAD): Loss-of-function variants: 12 observed, 27.19 expected, observed/expected ratio (o/e) 0.44, 90% interval 0.28 to 0.71. The upper end of that interval is the gene's LOEUF score, 0.71, which puts it in group 2 of 6, group 1 being the genes least tolerant of losing a copy. Missense variants: 566 observed, 680.19 expected, observed/expected ratio (o/e) 0.83, 90% interval 0.78 to 0.89. Synonymous variants: 304 observed, 269.43 expected, observed/expected ratio (o/e) 1.13, 90% interval 1.03 to 1.24.
Homologues: Orthologues: macaque MEX3C (98% identical), pig MEX3C (97% identical), chimpanzee MEX3C (96% identical), rat Mex3c (95% identical), mouse Mex3c (95% identical), guinea pig MEX3C (89% identical), dog MEX3C (85% identical), rabbit MEX3C (70% identical), tropical clawed frog mex3c (56% identical), Drosophila melanogaster CG11360 (33% identical), Caenorhabditis elegans mex-3 (27% identical). Paralogues in human: MEX3B (45% identical), MEX3D (40% identical), MEX3A (34% identical).
Diseases named in the same sentence as MEX3C in open-access papers:
MEX3C is named in the same sentence as 28 diseases in open-access papers, as found by Europe PMC text mining. Sharing a sentence is not in itself a finding about the gene and the disease. The quoted sentences say what the papers report.
colorectal cancer (4 papers, 2017 to 2023). A primary or metastatic malignant neoplasm that affects the colon or rectum. "MEX3C behaves as an oncogene in colorectal cancer, bladder cancer, and osteosarcoma, but its biological relevance in cervical cancer is unclear." (PMID 36439901, 2022). "By contrast, Mex3C was described as a new chromosomal instability (CIN) suppressor in CIN+ colorectal cancer." (PMID 28977858, 2017). "In colorectal cancer, MEX3C has been identified as an unstable gene that is frequently lost in CIN+ (cervical intraepithelial neoplasia+), and this protein was shown to regulate lipid metabolism through the JNK (c-Jun N-terminal kinase) pathway in bladder cancer and breast cancer." (PMID 36507941, 2023). "Using a bioinformatics approach, we narrowed down the targets of miR-451a to a group of 14 genes, which was further filtered to 4 genes –CAB39, EMSY, EREG and MEX3C based on either a known role in colorectal cancer or radiation responsiveness in other cancer types." (PMID 29720118, 2018). "We further narrowed this list by filtering genes with a known role in human colorectal cancer and/or cellular response to ionizing radiation that resulted in a group of four genes -CAB39, EMSY, EREG, and MEX3C." (PMID 29720118, 2018).
bladder cancer (3 papers, 2021 to 2023). "The activation of JNK signaling by MEX3C has been linked to bladder cancer development." (PMID 36439901, 2022). "A recent research indicates that MEX3C promotes bladder cancer development by regulating metabolism." (PMID 33896797, 2021).
hepatocellular carcinoma (3 papers, 2023 to 2025). A malignant tumor that arises from hepatocytes. "Ubiquitylation by upregulated MEX3C is involved in the progression of hepatocellular carcinoma." (PMID 38424632, 2024).
viral infection (3 papers, 2020 to 2023). "Moreover, mex-3 RNA binding family member C (MEX3C, also known as RNF194) also triggers the linkage of Lys-63-linked polyubiquitin to Lys45, Lys99, and Lys169 within the CARDs of RIG-I to promote the immune response against viral infection." (PMID 36980296, 2023). "MEX3C, TRIM4 and TRIM25 are the most important E3 ligases for positive regulation of RIG-I activity in response to viral infection, whereas RNF122 and RNF125 have been described to mediate the ubiquitin-dependent degradation of this cytosolic innate immune receptor." (PMID 32019099, 2020).
Anxiety (2 papers, 2023 to 2025). Intense feelings of nervousness, tension, or panic often arise in response to interpersonal stresses. "All these indicators were negatively correlated with anxiety‐like behavior, suggesting that the loss of the MEX3C gene can lead to increased anxiety‐like behavior." (PMID 37652868, 2023). "Mex3c KO leads to cognitive decline and anxiety in mice due to reduced neuron number and synapse plasticity." (PMID 37652868, 2023). "On the other hand, compared with WT mice, MEX3C‐KO mice showed increased anxiety‐like behaviors in minefield and elevated plus maze tests." (PMID 37652868, 2023).
Cognitive impairment (2 papers, 2023 to 2025). Abnormal cognition is characterized by deficits in thinking, reasoning, or remembering. "We also investigated whether MEX3C loss mediates cognitive impairment and mood dysregulation by affecting autophagy and apoptosis in the brain." (PMID 37652868, 2023). "Therefore, is cognitive impairment in mice caused by the deletion of the MEX3C gene also caused by the inhibition of autophagy resulting from the deletion of the MEX3C gene?" (PMID 37652868, 2023). "Our findings demonstrate that Mex3c KO mice exhibit pronounced social deficits and cognitive impairments, accompanied by neuronal injury, synaptic alterations, and mitochondrial dysfunction." (PMID 40463420, 2025).
Obesity (2 papers, 2020 to 2026). Accumulation of substantial excess body fat. "For example, MEX-3C (also known as RKHD2) is an E3 ubiquitin ligase, which plays a role in apoptosis, translational repression, chromosomal instability, energy, homeostasis, obesity, and post-natal growth." (PMID 32717840, 2020). "Moreover, MEX3C expression is markedly reduced in the adipose tissue of HFD-fed mice, a condition commonly associated with obesity-induced adipose dysfunction." (PMID 41596407, 2026).
autism (1 paper, 2025). Persistent deficits in social interaction and communication and interaction as well as a markedly restricted repertoire of activity and interest as well as repetitive patterns of behavior. "This study aimed to investigate whether Mex3c-deficient mice exhibit an increased tendency toward autism-like behaviors." (PMID 40463420, 2025). "Behavioral analysis showed that deletion of Mex3c increased autism-like and repetitive behaviors in mice." (PMID 40463420, 2025).
autism spectrum disorder (1 paper, 2025). A spectrum of developmental disorders that includes autism, and Asperger syndrome. "The damage of mitochondria is hypothesized to be a significant factor underlying autism spectrum disorder in mice resulting from the knockout of the Mex3c gene." (PMID 40463420, 2025).
cervical cancer (1 paper, 2022). A primary or metastatic malignant neoplasm involving the cervix. "MEX3C expression was shown to be significantly higher in cervical cancers compared to adjacent normal tissues." (PMID 36439901, 2022). "QRT-PCR results indicated that MEX3C expression was higher in cervical cancer cells than in normal cells." (PMID 36439901, 2022). "We discovered that in vitro, overexpression of MEX3C promoted the invasion, proliferation, and sphere formation of cervical cancer cells." (PMID 36439901, 2022). "Our western blotting results show that cervical cancer cells significantly reduced or raised MEX3C expression." (PMID 36439901, 2022). "In cervical cancer cells, circ_0004488 acted as a microRNA-136 (miR-136) sponge, increasing the expression of MEX3C (a direct target gene of miR-136) using dual-luciferase reporter assays." (PMID 36439901, 2022). "Using the Kaplan–Meier plotter database, we found that patients with cervical cancer and high MEX3C expression had significantly worse overall survival." (PMID 36439901, 2022). "According to the findings of a western blotting study, when cervical cancer cell lines were transfected with circ_000448 siRNA or miR-136 mimics, the protein levels of MEX3C were lowered." (PMID 36439901, 2022). "We analyzed MEX3C coexpressed genes in TCGA cervical cancer tissues using the LinkedOmics database." (PMID 36439901, 2022). "Human cervical cancer tissues were shown to express much more MEX3C than normal tissues." (PMID 36439901, 2022). "By suppressing MEX3C expression, cervical cancer cells became more sensitive to paclitaxel." (PMID 36439901, 2022). "As a result, we utilized siRNA that targets MEX3C or a MEX3C expression vector to evaluate whether downregulation or upregulation of MEX3C could affect the proliferation, invasion, sphere formation, and paclitaxel resistance in cervical cancer cells." (PMID 36439901, 2022). "Circ_0004488 serves as an important miR-136 sponge, preventing the development of cervical cancer and PTX resistance via the miR-136/MEX3C axis." (PMID 36439901, 2022).
deficiencies (1 paper, 2025). "Our preliminary research has demonstrated that Mex3c gene inactivation in mice causes both neurodevelopmental deficiencies and an increased probability of cognitive and nervous disorders, suggesting Mex3c as a possible new risk gene for ASD." (PMID 40463420, 2025).
diabetic kidney disease (1 paper, 2021). Progressive kidney disorder caused by vascular damage to the glomerular capillaries, in patients with diabetes mellitus. "In diabetic kidney disease (DKD), MEX3C-driven poly-ubiquitination of PTEN promotes EMT, as indicated by enhanced interstitial matrix deposition." (PMID 34067172, 2021).
lung carcinoma (1 paper, 2024). "The results above indicated that MEX3C could accelerates lung cancer metastasis in vivo." (PMID 38424632, 2024).
mental retardation (1 paper, 2023). "The specific mechanism of MEX3C deficiency leading to mental retardation in offspring may be related to the inhibition of neuronal autophagy and the abnormal activation of apoptosis." (PMID 37652868, 2023).
ovarian carcinoma (1 paper, 2021). A malignant neoplasm originating from the surface ovarian epithelium. "In conclusion, this study demonstrated that circ_0007841/miR-151-3p/MEX3C axis exerted important oncogenic functions in ovarian cancer." (PMID 33896797, 2021).
cancer (7 papers, 2017 to 2024). A tumor composed of atypical neoplastic, often pleomorphic cells that invade other tissues. "Despite the fact that miR-136 is expected to have a wide number of downstream target genes, we chose MEX3C for our investigation since it has been linked to cancer development and chemoresistance stem cells." (PMID 36439901, 2022). "MEX3C mRNA levels were higher in LUAD cancer tissues than in normal paraneoplastic tissues, while RUNX3 expression trended in the opposite direction." (PMID 38424632, 2024). "Despite the fact that it is widely expressed in a variety of tissues, however, very little is known about the role that another essential member plays in cancer: MEX3C." (PMID 38424632, 2024). "We evaluated the expression distribution of MEX3C between tumor and normal tissues in TCGA + GTEx pan-cancers dataset." (PMID 38424632, 2024). "The RNA-binding ubiquitin ligase MEX3C promotes tumorigenesis in several cancers but its mechanism of action in LUAD is unclear." (PMID 38424632, 2024). "The pan-cancer profiles analysis showed that MEX3C expressed at relatively higher levels in most kinds of tumor tissues than in normal tissues." (PMID 38424632, 2024). "MEX3C is a protein with two K homology (KH) RNA-binding domains that has a role in energy metabolism, immune response, and cancer growth." (PMID 36439901, 2022). "This study demonstrated that miR-136 binds to the 3′-UTR of MEX3C mRNA, influencing energy metabolism, immune response, and cancer development." (PMID 36439901, 2022). "Although the ubiquitylation and degradation of RUNX3 has been reported in other cancer types, the role of MEX3C as the specific E3 ubiquitin ligase regulating this process in LUAD remains unknown." (PMID 38424632, 2024). "Both RNF20 and Mex3c are considered as tumor suppressive genes in cancer." (PMID 29066742, 2017). "To explore the role of the MEX3 family in cancers, we used TCGA for pan-cancer analysis of the expression of MEX3A, MEX3B, MEX3C and MEX3D." (PMID 38914858, 2024). "Given the parallels with our findings, therapeutically targeting ubiquitylation enzymes like MEX3C and MEX3A may hold promise as an innovative strategy to suppress tumorigenesis in cancers where they play an oncogenic role." (PMID 38424632, 2024).
tumor (7 papers, 2017 to 2024). "Tumor volume and weight were significantly reduced by the suppression of MEX3C in both LUAD cell lines." (PMID 38424632, 2024). "In the present study, we have demonstrated that MEX3C is upregulated in LUAD tumor tissue whereas RUNX3 is downregulated." (PMID 38424632, 2024). "Altogether, these findings indicate that Knockdown of MEX3C promotes apoptosis and inhibits proliferation in LUAD cells, MEX3C plays a substantial role in the tumor progression of LUAD." (PMID 38424632, 2024). "Univariate Cox analysis showed that MEX3C expression (HR: 2.211, 95% CI: 1.233–4.204), gender (HR: 0.053, 95% CI: 0.269–0.942) and tumor stage (HR: 8.291, 95% CI: 1.140-60.306) were independent prognostic factors for HCC patients." (PMID 37828435, 2023). "We integrated clinicopathological factors (gender and tumor stage) and MEX3C expression levels to predict 1-, 2-, 3-, and 5-year survival probabilities of patients in the clinic." (PMID 37828435, 2023). "The results of the present study showed that MEX3B and MEX3C expression was positively related to tumour purity and CD8+ T cell and CD4+ T cell infiltration." (PMID 36507941, 2023). "MEX3C exhibits associations with various immunosuppressive pathways, including TGF-β, MDSCs, and Tregs, while also augmenting the tumor-suppressive impact of Lenvatinib." (PMID 37828435, 2023). "Tumor tissues from the circ_000448 vector group showed a decrease in miR-136 and an increase in MEX3C after qRT-PCR analysis, in contrast to those from the control vector group." (PMID 36439901, 2022). "Circ_0007841 knockdown suppressed tumor growth while miR-151-3p inhibition or MEX3C overexpression recovered tumor propagation." (PMID 33896797, 2021). "In addition, TUNEL staining showed that the number of green-stained positive cells was significantly decreased after treatment with si-MEX3C compared with the si-NC group, indicating that MEX3C significantly promoted apoptosis of tumor cells." (PMID 38424632, 2024). "Besides, the mRNA expression of MEX3C increased with tumor grade was the highest in stages III to IV." (PMID 38424632, 2024). "This indicates that not only does MEX3C interact with RUNX3 in LUAD cells but other factors controlled by RUNX3 could be contributing to tumor progression." (PMID 38424632, 2024). "Targeting the MEX3C gene could potentially influence immunosuppressive cells in the tumor microenvironment, including regulatory T cells and MDSCs, potentially enhancing the efficacy of immunotherapy." (PMID 37828435, 2023). "In addition, TIMER analysis revealed that MEX3B and MEX3C were positively related to tumour purity and CD8+ T cell and CD4+ T cell infiltration." (PMID 36507941, 2023). "MEX3B and MEX3C were positively correlated with tumour purity, CD8+ T cells and CD4+ T cells." (PMID 36507941, 2023). "Western blotting results of the tumor tissue also confirmed that proliferation and EMT were inhibited by the suppression of MEX3C." (PMID 38424632, 2024). "Our objectives are to investigate the effects of MEX3C on LUAD cell proliferation, apoptosis, migration and invasion in vitro and tumor growth and metastasis in vivo." (PMID 38424632, 2024). "Inversely, the mRNA expression of RUNX3 in LUAD tissues decreased with tumor grade and a significantly negative correlation was obtained by Pearson analysis between the mRNA expression of MEX3C and RUNX3 (P < 0.0001, r = − 0.6151)." (PMID 38424632, 2024). "In the tumor tissue derived from A549 and H2199 NSCLC cells, protein levels of RUNX3 were increased when MEX3C was inhibited but Suv39H1 protein levels were lower, indicating that RUNX3 could negatively control Suv39H1." (PMID 38424632, 2024). "In the cox retrospective analysis of the TCGA database, MEX3C was not affected by tumor stage and was an independent prognostic factor." (PMID 37828435, 2023).
neurodevelopmental disorder (1 paper, 2025). A behavioral and cognitive disorder with onset during the developmental period that involves impaired or aberrant development of intellectual, motor, or social functions. "Previous research has also shown that Mex3c participates in neural development, energy metabolism, and immune regulation, providing a plausible biological basis for its involvement in neurodevelopmental disorders." (PMID 40463420, 2025). "Although the direct involvement of Mex3c in ASD remains to be confirmed, our study provides new insights into the functional role of Mex3c in brain development and behavior, highlighting it as a candidate gene for further investigation in neurodevelopmental disorders." (PMID 40463420, 2025).
MEX3C also shares sentences with these, for which no sentence is quoted: lung adenocarcinoma (2 papers); breast carcinoma (1); cervical intraepithelial neoplasia (1); cognitive decline (1); ductal carcinomas (1); glioma (1); melanoma (1); memory impairment (1); osteosarcoma (1); Sepsis (1).